ABCA7 (ATP binding cassette subfamily A member 7)
Diseases named in the same sentence as ABCA7 in open-access papers (continued):
Sharing a sentence is not in itself a finding about the gene and the disease.
schizophrenia (2 papers, 2009 to 2012). A major psychotic disorder characterized by abnormalities in the perception or expression of reality. "A single nucleotide polymorphism (SNP) of ABCA7 has been found to be associated with schizophrenia." (PMID 23029339, 2012). "We typed 11 and 5 SNPs for the ABCA1 and ABCA7 genes to test whether these genes in the phagocytosis pathway may impact on risk for schizophrenia." (PMID 19721717, 2009). "A SNP of ABCA7 has been found to be associated with schizophrenia and ABCA7’s role in phagocytosis might impact on the deregulation of apoptosis in cortical regions of schizophrenia patients." (PMID 23029339, 2012). "To test whether other CED orthologs in human are involved in schizophrenia, we conducted association analyses of the GULP1, ABCA1 and ABCA7 genes that are the human orthologs of the CED-6 and CED-7 genes." (PMID 19721717, 2009).
Tangier disease (2 papers, 2022). "Two of the studied ABCA7 mutants, p.A845V and p.R1932C, are in conserved amino acid residues and mutations at these residues in ABCA1 or ABCA4 are known to cause Tangier disease or Stargardt disease respectively." (PMID 35361255, 2022). "Despite the high homology between ABCA1 and ABCA7, the latter does not compensate for the loss of ABCA1 in Tangier disease patients, further questioning the exact role of ABCA7 in cellular cholesterol release." (PMID 35477481, 2022).
tauopathy (2 papers, 2019 to 2020). Neurodegenerative disorders involving deposition of abnormal tau protein isoforms (tau proteins) in neurons and glial cells in the brain. "Meanwhile, ABCA7 rs115550680 directly impacts the brain through Aβ facilitated tauopathy, which negatively influences MTL functional connectivity, and consequently, behavioral generalization." (PMID 31749691, 2019).
asthma (1 paper, 2024). "ABCA7 gene expression is associated with nocturnal asthma symptoms in individuals with a polymorphism in NPSR1." (PMID 38540988, 2024).
atherosclerosis (1 paper, 2012). A disease characterized by the build-up of fatty material and calcium deposition in the arterial wall resulting in partial or complete occlusion of the arterial lumen. "In the current study, we investigated the in vivo effects of macrophage ABCA7 deficiency on lipid metabolism and atherosclerosis." (PMID 22403608, 2012). "Still, a positive correlation between the amount of foam cells and the susceptibility to atherosclerosis was found, indicating that atherogenesis, under the conditions studied, is likely to occur independently of an anticipated role for ABCA7 in phagocytosis." (PMID 22403608, 2012). "All together, ABCA7 has been implicated in several physiologically important pathways, nevertheless its role in macrophage foam cell formation in vivo and atherosclerosis remains unknown." (PMID 22403608, 2012). "Despite the decreased serum lipid levels in ABCA1 KO and ABCA1/ABCA7 dKO transplanted mice, significantly higher amounts of foam cells were observed in the peritoneal cavity of these animals compared to controls, while also the susceptibility to atherosclerosis was increased." (PMID 22403608, 2012). "Increased macrophage ABCA1 expression might thus counteract the effect of ABCA7 deletion in foam cell formation and atherosclerosis." (PMID 22403608, 2012). "Therefore, in addition to the anticipated role of ABCA7 in cholesterol homeostasis and cholesterol efflux, ABCA7 may also affect atherosclerosis by its role in phagocytosis, which can be pro- or antiatherogenic." (PMID 22403608, 2012). "Interestingly, dKO transplanted mice, thus, showed a less severe increase in both foam cells and atherosclerotic lesion size compared with ABCA1 KO transplanted mice, indicating that ABCA7 deletion attenuates the effect of ABCA1 deletion on foam cell formation and atherosclerosis." (PMID 22403608, 2012).
bladder cancer (1 paper, 2025). "To investigate the protein expression profiles of six genes (ABCA7, HOOK2, JUNB, RHOB, VMP1, and ACTG1) that significantly impact both DSS and PFI in bladder cancer patients, we conducted Western blot analyses using SV-HUC-1 and 5637 cell lines." (PMID 40574864, 2025).
Brain atrophy (1 paper, 2019). Partial or complete wasting (loss) of brain tissue that was once present. "In summary, evidence is presently linking AD-associated ABCA7 common variants to increased brain atrophy already at preclinical stages of AD." (PMID 30903345, 2019).
COVID-19 (1 paper, 2021). A disease caused by infection with severe acute respiratory syndrome coronavirus 2. "There is no study showing a direct link between the ABCA7 gene and COVID-19 yet, but it has been proven that it is highly expressed in the reticuloendothelial system and modulates the phagocytosis activity, though its function, like many other ABC-transporters, has yet to be clarified." (PMID 34828448, 2021).
leukemia (1 paper, 2022). A malignant (clonal) hematologic disorder, involving hematopoietic stem cells and characterized by the presence of primitive or atypical myeloid or lymphoid cells in the bone marrow and the blood. "We next determined the effect of SNDX-5613 on in vivo leukemia-initiating potential of primary PD AML cells harboring MLL-AF9 plus FLT-3 N676T, as well as mutations in KMT2C, KMT2D, NOTCH2, IRF8, ARID1A, VPS13A, and ABCA7, which were determined by whole-exome sequencing." (PMID 35017466, 2022).
primary progressive aphasia (1 paper, 2022). Primary progressive aphasia (PPA) is a neurodegenerative disorder, characterized by a primary dissolution of language, with relative sparing of other mental faculties for at least the first 2 years of illness. "A partial deletion in the ABCA7 gene and a variant in the GRN gene has been found in a patient with semantic variant of primary progressive aphasia, one of the clinical phenotypes associated with FTLD-TDP." (PMID 36385764, 2022).
retinoblastoma (1 paper, 2025). A malignant tumor that originates in the nuclear layer of the retina. "In retinoblastoma, the Y79 cell line demonstrates high gene expression of ABCA7 along with several other ABC transporters." (PMID 40214466, 2025). "This elevated expression suggests that ABCA7 might be a potential target for medical treatment of retinoblastoma." (PMID 40214466, 2025).
Splenomegaly (1 paper, 2012). Abnormal increased size of the spleen. "Interestingly, combined deletion of bone marrow ABCA1 and ABCA7 causes severe splenomegaly associated with cellular lipid accumulation, a reduction in splenic CD3+ T cells, and induced markers of erythropoeisis." (PMID 22403608, 2012). "Since dKO transplanted mice exhibited severe splenomegaly, associated with a decrease in CD3+ T cells and increased markers of erythropoiesis, ABCA7 might have a role in hematopoiesis in spleen." (PMID 22403608, 2012). "Interestingly, severe splenomegaly was observed in dKO transplanted mice, whereas no such phenotype was present in WT, ABCA1 KO, and ABCA7 KO transplanted mice." (PMID 22403608, 2012).
Stargardt disease (1 paper, 2022). "Also, among the rare ABCA7 missense mutations, we observed mutations that affect amino acid residues that are conserved in ABCA1 and ABCA4, of which some correspond to established ABCA1 or ABCA4 disease-causing mutations involved in Tangier or Stargardt disease." (PMID 35361255, 2022).
vascular dementia (1 paper, 2019). A degenerative vascular disorder affecting the brain. "Finally, a recent study examined the effect of ABCA7 sentinel SNP rs4147929 on vascular dementia, ischemic heart disease, ischemic cerebrovascular disease, and lipid levels in 104,258 individuals from the Danish general population, but did not observe an association with these endophenotypes." (PMID 30903345, 2019).
cancer (11 papers, 2013 to 2025). A tumor composed of atypical neoplastic, often pleomorphic cells that invade other tissues. "All these findings suggest an association of ABCA7 with various types of cancer." (PMID 37296582, 2023). "Interestingly, while evidence is limited compared to neurodegenerative diseases, ABCA7 has also been linked to cancer." (PMID 30903345, 2019). "However, the role and underlying mechanism of ABCA7 in cancer are yet to be discovered." (PMID 37296582, 2023). "Hence, while more research is needed, it seems that an increase of ABCA7 expression may lead to a higher risk of specific cancer-type development, which is opposite to ABCA7 loss-of-function as a pathomechanism of AD." (PMID 30903345, 2019). "The antagonistic role of RHOB and ABCA7 in cancer reveals that there are complex interactions among Hub-EGFR.Sig, which was also confirmed in our subsequent miRNA–mRNA and TF-mRNA interactive network analysis." (PMID 40574864, 2025). "This is found downregulated in OVACAR-3 cells as well as in other types of cancer cells such as hepatocarcinoma cells, suggesting a potential implication of ABCA7 in other types of cancers." (PMID 33925691, 2021). "Further investigations for the ABCA7 role in cancer are needed for a better understanding of this transporter functions and for a better diagnosis and prognosis." (PMID 33925691, 2021). "In this study, authors demonstrated that ABCA7 was upregulated in ovarian cancer (OC) cells from patients when compared to adjacent non-cancer tissues." (PMID 33925691, 2021). "This is noteworthy because ABC transporters have been closely linked to the MDR phenotype observed in cancer cells in the most recent studies of ABCA7 in cancer." (PMID 33925691, 2021). "To date, dysregulation of ABCA7 in cancer has been reported in only a few studies." (PMID 37296582, 2023). "Additionally, regulation of ABCA7 in cancer cells was reported to be modulated by the micro-RNA tumor suppressor called Mir-197-3p." (PMID 33925691, 2021). "They will also determine if targeting ABCA7 expression might be a promising approach to prevent or cure certain types of cancers." (PMID 33925691, 2021). "Our results indicate that intron retention and/or alternative intron termination, both resulting in non-functional ABCA7, is an important mechanism for cancer cells to cope with chemotherapy-induced stress." (PMID 37296582, 2023).
neurodegenerative disease (7 papers, 2012 to 2025). A disorder of the central nervous system characterized by gradual and progressive loss of neural tissue and neurologic function. "ABCA7 loss of function variants are enriched in both AD and Parkinson’s disease (PD) patients, suggesting a broad role across neurodegenerative diseases." (PMID 34859289, 2022). "However, a recent follow-up study of ABCA7 mutations challenges the assertion that all of these variants are loss of function, and implicates a role for ABCA7 in additional neurodegenerative diseases." (PMID 28549481, 2017). "Lastly, PSEN2 Thr421Met may interact with other mutations in neurodegenerative disease related genes, which were found in the proband patient, such as ATP binding cassette subfamily A member 7 (ABCA7), Notch Receptor 3 (NOTCH3), or Leucine-rich repeat kinase 2 (LRRK2)." (PMID 36362122, 2022). "In conclusion, this study is the first to provide a detailed analysis of Abca7 function in behavioural domains relevant to neurodegenerative diseases in vivo." (PMID 23029339, 2012). "This strategy will provide information about the potential involvement of Abca7 in a variety of behavioural domains with a particular focus on those relevant to neurodegenerative diseases." (PMID 23029339, 2012).
neurological disorders (3 papers, 2021 to 2024). "Differentially expressed or spliced genes in the compound heterozygous mutant animals include ortholougus genes causing human neurological disorders such as Abca7, Zfp365, Kmt2c, Madd and Tcf4." (PMID 37294900, 2024). "Imaging of ABC transporters of the BBB has already been accomplished before, and the results of the present study found the basis for PET tracer development of other, yet under-studied ABC transporters involved in neurological disorders like AD, as for example, ABCA7." (PMID 34976306, 2021).
tumor (3 papers, 2023 to 2025). "We investigated if the ABCA7 DNA methylation status in tumor tissues is associated with expression of Ki-67, a cellular marker for proliferation." (PMID 37296582, 2023). "By investigating transcript levels of human ABC transporters in pancreatic ductal adenocarcinoma, ABCA7 was one of 20 ABC transporters found to be significantly up-regulated in tumor tissues compared to adjacent non-neoplastic tissues." (PMID 37296582, 2023).
brain disorder (1 paper, 2012). A disease affecting the brain or part of the brain. "A potential role of ABCA7 in the development of brain disorders has recently been suggested." (PMID 23029339, 2012).
ABCA7 also shares sentences with these, for which no sentence is quoted: Parkinson disease (4 papers); amyotrophic lateral sclerosis (3); allergic disease (2); autism spectrum disorder (2); frontotemporal dementia (2); infection (2); allergic asthma (1); autoimmune disease (1); Barth syndrome (1); behavioral variant frontotemporal dementia (1); brain tumors (1); breast tumor (1); cardiovascular disease (1); Dystonia (1); epilepsy (1); epilepsy syndrome (1); glioblastoma (1); hyperlipidemia (1); Hypertension (1); Intellectual disability (1); ischemia (1); ischemic stroke (1); Lewy body dementia (1); memory impairment (1); movement disorder (1); osteosarcoma (1); psychiatric disorder (1); Sepsis (1); Stroke (1).